RNU6-513P (RNA, U6 small nuclear 513, pseudogene)
Gene: Small nuclear RNA gene on chromosome 22 (42,569,147 to 42,569,250, reverse strand). Ensembl gene ENSG00000251913.
Homologues: Orthologues: chimpanzee U6 (100% identical), macaque U6 (89% identical), macaque U6 (87% identical), dog U6 (72% identical), pig U6 (69% identical). Paralogues in human: RNU6-24P (82% identical), RNU6-727P (82% identical), RNU6-1011P (81% identical), RNU6-1243P (81% identical), RNU6-1029P (80% identical), RNU6-12P (80% identical), RNU6-13P (80% identical), RNU6-16P (80% identical), RNU6-22P (80% identical), RNU6-32P (80% identical), RNU6-338P (80% identical), RNU6-33P (80% identical), and 1288 more.